TMEM18 (transmembrane protein 18)
Diseases named in the same sentence as TMEM18 in open-access papers (continued):
Sharing a sentence is not in itself a finding about the gene and the disease.
Obesity (continued). "The expression levels of other eight obesity-related genes (TMEM18, KCTD15, GNPDA2, SH2B1, FTO, LEP, PCSK1, and GPR120) in about half types of cancer tissues were higher/lower than those in the corresponding normal tissues." (PMID 33299884, 2020). "Further functional studies are needed to understand the mechanisms by which the locus near TMEM18 (rs6548238) regulates the development of obesity and type 2 diabetes." (PMID 32228543, 2020). "In addition, subjects with CC or CT genotypes of rs6548238 had elevated waist circumference, waist/hip ratio, BMI, fasting plasma glucose, HbA1c, TG, and TC, but declined HDL-C, suggesting that the locus near TMEM18 (rs6548238) may increase obesity/diabetes risk through inducing metabolic disorders." (PMID 32228543, 2020). "TMEM18 is a highly conserved gene related to obesity and plays a role in the central control of appetite and body weight regulation." (PMID 30993211, 2019). "Several studies have examined the effect of obesity-risk genes, such as FTO, MC4R, and the transmembrane protein 18 (TMEM18) on GWG." (PMID 29686896, 2018). "Our findings implicate many genes previously associated with obesity (e.g. PTBP2, TMEM18, MYT1L, POU3F2, SIM1, SH2B1), and also identified other potentially relevant candidates including TAS1R3, ALOX5AP, and GAS6." (PMID 29441128, 2018). "The strongest reported SNP associations for BMI are provided by rs1558902 (FTO) and rs13021737 (TMEM18), which have a well-established impact on obesity." (PMID 27336604, 2016). "TMEM18 is ubiquitously expressed, and although a direct link to obesity is still elusive, early evidence suggests a likely role through transcriptional regulation of critical targets." (PMID 26075635, 2015). "Three BMI-increasing alleles of SNPs in or near TMEM18 and PCSK1 were nominally associated with increased risk of obesity (OR was 1.45 and 1.23, P = 0.002 on a binomial test)." (PMID 24626232, 2014). "PCA-based method has been also applied to detect different kinds of TMEM18-BDNF interactions on obesity." (PMID 24059907, 2013). "FTO, TMEM18 and INSIG2 variants showed the most significant associations with obesity in this population." (PMID 23950976, 2013). "After adjusting for age, sex and admixture, significant associations with obesity were found for 6 genes in the case-control study (ADIPOQ, FTO, TMEM18, INSIG2, FAIM2/BCDIN3 and BDNF)." (PMID 23950976, 2013). "Other loci, including the INSIG2, TMEM18, KCTD15, SH2B1, MTCH2, GNPDA2, BDNF, or CHST8 genes, have also been associated with obesity." (PMID 24267414, 2013). "SNPs in the FTO, GNPDA2, SEC16B, BDNF, TMEM18 and NPC1 loci associated with increased risk of both overweight and obesity." (PMID 23861046, 2013). "Common variations at the loci harboring the fat mass and obesity gene (FTO), MC4R, and TMEM18 are consistently reported as being associated with obesity and body mass index (BMI) especially in adult population." (PMID 24348519, 2013). "Of the 53 previously established obesity/adiposity loci we examined in the discovery dataset, only one had p<0.001 (rs6548238 SNP in the TMEM18, p = 8.15×10−4 in the combined-age adjusted set)." (PMID 22479309, 2012). "A few smaller GWAs focused on other forms of obesity (early onset, extreme obesity and/or morbid adult obesity) and replicated FTO, MC4R and TMEM18 BMI-associations." (PMID 21466928, 2011). "Although, the studies related to obesity highlight the expression of TMEM18 in brain, it is expressed robustly in most of the tissues studied in human, mouse, rat, and fruit fly." (PMID 21980424, 2011). "The TMEM18 gene was presented as a hypothalamic gene by the earlier study reporting the GWA to obesity." (PMID 20380707, 2010). "We observed that genetic variants in or near FTO, MC4R, TMEM18, SDCCAG8, and TNKS/MSRA were robustly associated with early-onset obesity." (PMID 20421936, 2010).
Obesity (continued). "The obesity-risk-allele score based on genotypes at eight SNPs associated with childhood BMI (in/near to: FTO, MC4R, TMEM18, GNPDA2, NEGR, KCTD15, BDNF, and ETV5) ranged from 2 to 15 alleles." (PMID 20520848, 2010). "Furthermore, this is fundamental nutrigenetic evidence regarding TMEM18 gene’s relation to obesity in the Israeli population." (PMID 36678137, 2023). "Where TMEM18 rs939583 ALT allele heterozygotes and homozygotes carriers who consume wine in moderation significantly reduced their obesity risk by 40 and 35%, respectively, compared to ALT allele heterozygotes and homozygotes carriers who did not consume any wine." (PMID 36678137, 2023). "Moreover, TMEM18 expression in adipocytes is attenuated in children and adults with obesity, as well as with obesity-induced adipose tissue and metabolic dysregulation, such as in insulin resistance." (PMID 36986146, 2023). "They showed that the expression of TMEM18 varies in adipose tissue of children without excess adiposity, depending on the presence of the obesity risk allele in rs7561317 and rs17729501 polymorphisms." (PMID 36986146, 2023). "The present study aimed to identify associations linking allelic variants of the PCSK1, TMEM18, GPX5, ZPR1, ZBTB16, and PPARG1 genes with anthropometric and biochemical traits and metabolic diseases (obesity or metabolic syndrome) in an adult population from northwestern Mexico." (PMID 37761915, 2023). "Selected ORGs expression, namely the fat mass and obesity-associated (FTO), melanocortin-4 receptor (MC4R), glucosamine-6-phosphate deaminase 2 (GNPDA2), and transmembrane protein 18 (TMEM18) were evaluated in testes and spermatozoa by a quantitative polymerase chain reaction (qPCR)." (PMID 36289871, 2022). "Therefore, the current study has been undertaken to compute the GRS based on five obesity-linked key loci including MC4R rs17782313, BDNF rs6265, FTO rs1421085, TMEM18 rs7561317, and NEGR1 rs2815752 in this at-risk and under-represented population." (PMID 33859285, 2021). "With the discovery of an apparent relationship between the TMEM18 region and obesity, there is a clear need to determine more precisely the effect size of polymorphisms rs6548238, rs4854344, rs11127485, rs2867125, and rs7561317 localised near the gene itself with regard to age and population type." (PMID 34229657, 2021). "The findings from the present study provide no consistent statistically significant evidence for an association of the five investigated obesity-associated genes (FTO, TMEM18, MC4R, SEC16B, and BDNF) with baseline anthropometric traits or their changes after 12 months of behavioural intervention." (PMID 33801339, 2021). "Apart from its involvement in obesity, TMEM18 may also influence cell migration by regulating neuronal stem cell mobility." (PMID 34229657, 2021). "Taken together, among seven common obesity risk loci, the loci near TMEM18 (rs6548238), CDKAL1 (rs7754840), and FAIM2 (rs7138803) are associated with obesity, and loci near TMEM18 (rs6548238) and FAIM2 (rs7138803) are susceptibility loci for obese type 2 diabetes." (PMID 32228543, 2020). "Among 11 SNPs showing a higher frequency of rare alleles in participants without obesity, 7 mapped to the TMEM18 locus." (PMID 31649740, 2019). "We observed a significant association between TMEM18 (rs7561317) and children obesity; however, we did not observe significant association between adipokines and obesity in our study." (PMID 31354816, 2019). "Authors analyzed the genetic variants that cause lifelong high BMI in FTO (fat mass and obesity-associated gene, rs9939609), MC4R (Melanocortin-4 Receptor gene, rs17782313) and TMEM18 (transmembrane protein 18, rs6548238) genes to evaluate the consequences of the obesity in COPD patients." (PMID 28335527, 2017). "This not only highlights the potentially significant role of this SNP in the context of obesity, but may also represent the highly significant heterophilicity of TMEM18 within the SEN." (PMID 26715945, 2015).
Obesity (continued). "The TMEM18 gene (Transmembrane Protein 18) was marked by a SNP at BTA1 associated with trait K (maturity rate) and has been reported to be associated with growth traits and obesity." (PMID 26445451, 2015). "Although the biological effect of such interactions within TMEM18 is unknown, these interactions may influence the gene’s function and obesity through regulatory and epigenetic mechanisms." (PMID 26715945, 2015). "In addition, 7 of the 17 (41.2%) GWAs-selected genes (FTO, TMEM18, INSIG2, FAIM2/BCDIN3, BDNF, SH2B1 and MC4R) were associated with obesity in this population." (PMID 23950976, 2013). "From the beginning of 2009 there has been a spate of articles linking TMEM18 to obesity." (PMID 21980424, 2011). "Transmembrane protein 18 (TMEM18) has previously been connected to cell migration and obesity." (PMID 21980424, 2011). "Nine loci have been associated with extreme obesity at the genome-wide level, five of them influencing BMI / waist circumference as well as risk for extreme obesity (FTO, MC4R, TMEM18, MSRA, NPC1), four loci being more specific of genetic risk for extreme obesity (MAF, PTER, PRL, SDCCAG8)." (PMID 22043164, 2011). "TMEM18 was first proposed as an important obesity-related locus by the GIANT consortium." (PMID 20380707, 2010). "In addition, we assessed the effect of the markers in 31,182 obese, lean, normal weight, and unselected individuals from population-based samples and showed that the variants near FTO, MC4R, TMEM18, and SDCCAG8 were consistently associated with obesity." (PMID 20421936, 2010). "In conclusion, the results show that a region near TMEM18 is significantly contributing to obesity in severely obese children, a group that arguably has the highest genetic component and greatest need for healthcare among different population subgroups of obese individuals." (PMID 20380707, 2010). "It should be noted that while the risk contribution of the TMEM18 locus to obesity in adults has been examined, no attempt to determine such association has been made in obese children." (PMID 20380707, 2010). "In conclusion, we show that common variations nearby the TMEM18 gene are associated not only to adult obesity but also obesity in severely obese children in a similar magnitude as FTO, the first gene associated with the common form of obesity." (PMID 20380707, 2010). "We found that loci near TMEM18 (rs6548238), CDKAL1 (rs7754840), and FAIM2 (rs7138803) may be associated with obesity-related indicators, and loci near TMEM18 (rs6548238) and FAIM2 (rs7138803) may increase susceptibility of concurrent type 2 diabetes associated with obesity." (PMID 32228543, 2020). "Thus, the molecular structure of the TMEM18 protein is very uncommon in terms of other proteins in the human genome and surely very much different compared to other proteins involved in obesity, such as the enzyme FTO and the G protein-coupled melanocortin receptor, MC4R." (PMID 20380707, 2010). "Thus, we demonstrate that the currently known major common variants related to obesity overlap to a substantial degree between children and adults confirming previous observations for FTO, MC4R, TMEM18, NEGR1 and extending this observation to SEC16B, BDNF and BCDIN3D;." (PMID 20421936, 2010). "According to a recent study, TMEM18 is an upstream regulator of PPARG signaling driving healthy adipogenesis, which is dysregulated with adipose tissue dysfunction and obesity." (PMID 41082226, 2025). "The expression level of each of the five obesity-related genes (SH2B1, GNPDA2, FTO, TMEM18, and KCTD15) in three cancer tissues (HNSC, LIHC, and CHOL) was higher than that in the corresponding normal tissues." (PMID 33299884, 2020). "Some genes from this group are the fat mass and obesity (FTO), melanocortin-4 receptor (MC4R), and the transmembrane protein 18 (TMEM18)." (PMID 33324496, 2020).
Obesity (continued). "The gene transmembrane protein 18 (TMEM18) is expressed in several regions of the brain, including the hypothalamus, which is responsible for the regulation of feeding behavior, and has a key role in energy regulation and obesity pathogenesis." (PMID 41082226, 2025). "Human SCs express obesity-related genes (ORG, MC4R, GNPDA2, TMEM18, and FTO), and the expression of GNPDA2 and TMEM18 proteins in SCs has been reported to increase after incubation with leptin and ghrelin, leading to a modulation of the nutritional support provided for spermatogenesis." (PMID 38961093, 2024). "Among these, only survival probability of KIRC patients could be impacted by gender and expression levels of four obesity-elated genes (LEP, MC4R, TMEM18, and PCSK1)." (PMID 33299884, 2020). "Although the mechanism of most genetic loci predispose individuals to obesity is not clear so far, evidence indicated that they were involved in energy uptake (FTO, MC4R, PCSK1, and BDNF) and adipocyte differentiation (FTO, TMEM18, BDNF, MTCH2 and NEGR1)." (PMID 24626232, 2014). "Of the individual SNP analyses, only rs6548238 near TMEM18, rs10838738 in MTCH2, and rs7498665 near SH2B1 showed nominally significant interactions with physical activity level on BMI or obesity risk, but none survived adjustment for multiple comparisons." (PMID 20824172, 2010). "Among the available phenotypes, obesity was chosen because it has been subjected to a number of high quality and well-powered GWAS that have identified more than 100 loci, many that have been consistently replicated across studies (e.g. FTO, BDNF, MC4R, TMEM18, SEC16B)." (PMID 33947323, 2021). "The comparison of changes in the expression levels of obesity-related genes between the occurrence of cancer and patients' survival revealed four obesity-related genes (LEPR, NEGR1, TMEM18, and SH2B1), which might play critical roles in preventing the progression and metastasis of kidney cancer." (PMID 33299884, 2020). "Hence, some obesity-related genes (LEPR, NEGR1, TMEM18, and SH2B1) may play critical roles in preventing progression and metastasis of kidney cancer." (PMID 33299884, 2020). "On the other hand, the lack of association of the other SNPs (TMEM18 rs6548238 C allele, GPX5 rs445870 G allele, ZPR1 rs964184 G allele, and ZBTB16 rs7106340 T allele) with metabolic diseases (obesity or metabolic syndrome) in this work could have been influenced by the sample size." (PMID 37761915, 2023). "Similarly the odds ratios for the respective obesity risk effect alleles did not vary strongly by group (children and adolescents vs. adults) with point estimates ranging between 1.35–1.45 (FTO), 1.35–1.45 (TMEM18) and 1.10–1.19 (SDCCAG8)." (PMID 20421936, 2010).
Insulin resistance (4 papers, 2017 to 2023). Increased resistance towards insulin, that is, diminished effectiveness of insulin in reducing blood glucose levels. "The abundance of FTO and TMEM18 in the spermatozoa of rats under CR were positively correlated with sperm concentration, while the testes’ TMEM18 expression was also positively correlated with sperm vitality and negatively correlated with insulin resistance." (PMID 36289871, 2022). "Despite the possible involvement of the GNDPA2, TMEM18, and ADCY3 loci in insulin resistance, insulin/glucagon regulation, and insulin secretion, respectively, we chose to retain them in the IV analysis." (PMID 28763444, 2017).
type 2 diabetes (3 papers, 2011 to 2020). "In this study, we found that CC or CT genotypes at the locus near TMEM18 (rs6548238) were most frequent in overweight/obese patients with type 2 diabetes." (PMID 32228543, 2020). "After adjusting for age and sex, CT or CC genotypes at the locus near TMEM18 (rs6548238) and AA or AG genotypes of the FAIM2 (rs7138803) locus were associated with type 2 diabetes." (PMID 32228543, 2020). "At the locus near TMEM18 (rs6548238), the CC genotype was most abundant in patients with overweight and type 2 diabetes (76.2%), and TT was most abundant in healthy controls (60.5%)." (PMID 32228543, 2020). "Univariate logistic regression analysis showed that the loci near TMEM18 (rs6548238) and FAIM2 (rs7138803) were associated with type 2 diabetes." (PMID 32228543, 2020). "The risk of type 2 diabetes has only been addressed in two other studies, and here association between TMEM18, GNPDA2, ETV5, FAIM2 and SH2B1 and a BMI-dependent increased risk of type 2 diabetes have been reported." (PMID 21912638, 2011). "After adjusting for sex and age, loci near TMEM18 (rs6548238) and FAIM2 (rs7138803), but not SH2B1 (rs7498665), near GNPDA2 (rs10938397), MTCH2 (rs10838738) and near MC4R (rs12970134), were associated with increased risk for type 2 diabetes in obese individuals." (PMID 32228543, 2020).
diabetes (2 papers, 2020 to 2023). "After adjusting for age and sex, the loci near TMEM18 (rs6548238) and FAIM2 (rs7138803) were significantly associated with diabetes." (PMID 32228543, 2020).
acute myeloid leukemia (1 paper, 2025). Acute myeloid leukemia (AML) is a group of neoplasms arising from precursor cells committed to the myeloid cell-line differentiation. "The prognostic potential of TMEM18 has been recognized in other malignancies, including acute myeloid leukemia (AML), highlighting its clinical significance." (PMID 40525903, 2025).
Alzheimer disease (1 paper, 2022). A progressive, neurodegenerative disease characterized by loss of function and death of nerve cells in several areas of the brain leading to loss of cognitive function such as memory and language. "DNA methylation level of TMEM18 was significantly correlated to the burden of neuritic amyloid plaques (NP), a key quantitative measure of Alzheimer’s disease neuropathology." (PMID 35461274, 2022).
glioblastoma (1 paper, 2023). The most malignant astrocytic tumor (WHO grade IV). "The transmembrane protein 18 gene (TMEM1; OMIM * 613220) is an evolutionarily highly conserved gene, encoding the nuclear transmembrane protein 18, which mediates the migration process of neural precursors to glioblastoma cells." (PMID 36986146, 2023).
kidney cancer (1 paper, 2020). Primary or metastatic malignant neoplasm involving the kidney. "However, patients with kidney cancer in the high-expression level group for each of TMEM18 and SH2B1 genes had a long life expectancy than those who in the low/medium-expression level group." (PMID 33299884, 2020). "Underexpressed LEPR, NEGR1, TMEM18, and SH2B1 genes prevented the progression and metastasis of kidney cancer." (PMID 33299884, 2020).
tumor (3 papers, 2013 to 2025). "In one tumor with MNA and its associated cell line, a few novel amplicons were found, which encompassed genes such as GDF7, FSHR, PRKCE, and TMEM18." (PMID 23656755, 2013). "Furthermore, we confirmed the prognostic significance of TMEM18 expression at the protein level with immunohistochemistry (IHC) in a primary PCa tumor cohort." (PMID 40525903, 2025).
TMEM18 also shares sentences with these, for which no sentence is quoted: metabolic disorders (3 papers); cancer (2); asthma (1); atrial fibrillation (1); cervical cancer (1); ischaemic heart disease (1); metabolic syndrome (1); morbid obesity (1); neurodevelopmental disorder (1); progressive supranuclear palsy (1); sarcopenia (1).